IL1B (interleukin 1 beta)
Diseases named in the same sentence as IL1B in open-access papers (continued):
Sharing a sentence is not in itself a finding about the gene and the disease.
sarcoidosis (continued). "Consistently, monocytes in sarcoidosis patients and, to a lesser extent in active TU, exhibited significantly increased enrichment of genes related to the ‘Inflammatory Response’, including IL1B, CXCL8 and TNF." (PMID 40469525, 2025). "The reason TNFα may be inferior to IL-1β at reflecting granuloma formation is unclear, but TNFα levels in sarcoidosis tissues are known to vary greatly based, in part, on disease activity." (PMID 37021060, 2023). "To further investigate the inflammatory capacity of patient exosomes with focus on innate responses, we added BALF exosomes from sarcoidosis patients or healthy individuals to allogeneic PBMCs and analysed the induction of IFNγ and IL-1β in different cell subsets." (PMID 32948789, 2020). "Sarcoidosis PBMCS were seen to produce significantly higher levels of IL-1β and IL-17." (PMID 30946009, 2019). "Our current study confirms our previous findings that IL-1β plays an important role in sarcoidosis." (PMID 30946009, 2019). "To determine whether increased pro-IL-1β expression in sarcoidosis leads to released IL-1β, we measured secreted IL-1β in the conditioned media of AMs and monocytes cultured in the absence or presence of LPS via ELISA." (PMID 30946009, 2019). "Therefore, we evaluated the expression of Glut1 and pro-IL-1β at baseline in AMs and monocytes from sarcoidosis and control subjects." (PMID 30946009, 2019). "We speculate that in sarcoidosis inhibition of lysosomal function by CHQ leads to increased proteasome degradation of HIF-α isoforms leading to subsequent inhibition of IL-1β and IL-17 cytokines production." (PMID 30946009, 2019). "The results indicated that active tuberculosis infection, NTM infection, lung abscess, other acute respiratory infections, cancer, AECOPD, AIP, and sarcoidosis positively correlated with serum IL-1B, while systemic CS or IS therapy led to a suppression in IL-1B expression." (PMID 30363691, 2018). "Similar conclusions were also drawn by other authors, who found that peripheral blood mononuclear cells (PBMNC) isolated from sarcoidosis patients released higher amounts of various cytokines involved in the pathogenesis of sarcoidosis (such as IL-1β, TNF-α, IL-6, and GM-CSF), compared to controls." (PMID 26445225, 2015). "However, the failure to demonstrate increased serum levels of IL-1β and IL-6 in sarcoidosis requires further investigation." (PMID 25866481, 2015). "Thus, in sarcoidosis increased IL-1β and IL-6 explains Th17 differentiation." (PMID 30946009, 2019). "Based on our results, 9 possible biomarkers were identified (IL-1β, IL-6, IL-8, IL-13, VEGF, angiogenin, C4a, RANTES, and MCP-1) out of 18 tested that significantly differ in the BALF of patients with HP and sarcoidosis." (PMID 40725075, 2025). "Targeted downregulation of HIF-1α via siRNA of sarcoidosis AMs led to a significant reduction (about 50%) in HIF-1α and pro-IL-1β protein expression." (PMID 30946009, 2019). "Alveolar macrophages isolated from patients with asbestosis, sarcoidosis and IPF have higher levels of IL-1β mRNA and spontaneous IL-1β secretion compared to control subject." (PMID 27001429, 2016). "However, the relative frequencies of CXCL8, IL1B, and M4SA1 transcripts were higher in TB samples whereas RORC mRNA was increased in the sarcoidosis samples." (PMID 38385142, 2023). "Enriched genes including MPO (myeloperoxidase), CXCL11, IL1A, CXCL10, FCGR3B, IL1B, TTN (titin), BATF2, VIP (vasoactive intestinal peptide), TLR3, CCR2, TLR7, and CR1 wereclosely related to sarcoidosis." (PMID 38137330, 2023). "Tamuraet al. showed that fibroblast outgrowths from transbronchial biopsies of nonfibrotic sarcoidosis lungs (n=7) produced more IL-6 after stimulation with IL-1β than biopsies from IPF lungs (n=4) and cancer lungs (n=5)." (PMID 36543347, 2022).
sarcoidosis (continued). "More recent data from Jenyet al. suggest that macrophages differentiated from monocytes isolated from patients with active sarcoidosis (n=26) were more sensitive to hypoxic challenge in vitro than those isolated from patients with inactive sarcoidosis, producing more TNF-α, IL-1β and TGF-β1." (PMID 36543347, 2022). "In the current study, we found that BALF exosomes from sarcoidosis patients, but not from healthy individuals, induced a dose-dependent elevation of intracellular IL-1β in monocytes." (PMID 32948789, 2020). "Furthermore, increased pro-IL-1β expression directly correlated with Glut1 and HIF-1α expression in sarcoidosis AMs." (PMID 30946009, 2019). "Sarcoidosis AMs and monocytes exhibit a phenotype resembling the Warburg effect or trained immunity exhibiting an abundance of HIF isoforms, higher expression for Glut1, and higher production of IL-1β and IL-17." (PMID 30946009, 2019). "To determine the relative contribution of increased HIF-1α in IL-1β production in sarcoidosis AMs, we transiently transfected sarcoidosis AMs with either non-targeted siRNA or HIF-1α targeted siRNA." (PMID 30946009, 2019). "In active sarcoidosis, AMs produce high amounts of CCL20, when stimulated by TNF-α and IL-1β." (PMID 24339826, 2013). "IL-1β (and not TNFα or IFNy) best reflects granuloma response in this in vitro model and, therefore, may be a useful biomarker for future clinical studies in sarcoidosis." (PMID 37021060, 2023).
cerebral malaria (27 papers, 2005 to 2025). A sequestration of Plasmodium falciparum in the brain, which can cause coma and/or seizures. "It was interesting to notice the increased levels of Tnf and Il1b in males which explains, at least in part, the higher mortality in this sex, since both cytokines are associated with cerebral malaria." (PMID 33841336, 2021). "Elevated levels of IFN-γ, TNF, IL-12, IL-6, IL-1β, and IL-10 are initially protective, although excessive serum levels of these cytokines are associated with cerebral malaria pathology." (PMID 22336003, 2012). "Recently, the IL1B 3953C>T polymorphism, which lies in exon 5 of IL1B, was reported to be associated with cerebral malaria in Gambia." (PMID 16098232, 2005). "Because the allele frequency of IL1B -31T is approximately 0.5 in the studied population, the present study yields a statistical power high enough for the detection of an association between IL1B -31T and cerebral malaria unless the association is very weak." (PMID 16098232, 2005). "Therefore, IL1B -31C>T is an important candidate polymorphism that may influence the susceptibility or resistance to cerebral malaria through the upregulation of IL-1β." (PMID 16098232, 2005). "Increased IL-1β levels in cerebral malaria were either directly or indirectly connected with brain oedema." (PMID 36309676, 2022). "Other inflammatory cytokines, such as interferon gamma (IFN-γ), interleukin-6 (IL-6), and IL-1β, are also elevated in adults and children with cerebral malaria, with circulating concentrations ranging between 0.01 and 1 ng/mL." (PMID 36036514, 2022). "Because cytokines TNF-α and IL-1β contribute to cerebral malaria pathogenesis in mice, we also evaluated the effect of 17β-estradiol on the mRNA expression of pro-inflammatory cytokines in the brain." (PMID 33841336, 2021). "As the infection of CBA/Ca mice with P. berghei ANKA is the gold standard model for the investigation of cerebral malaria, we also analyzed mRNA expression levels of Tnf, Il1b, and Il10 in the brains of male and female mice treated with 17β-estradiol." (PMID 33841336, 2021). "IL-1β also has been detected in histopathological sections from patients who died of cerebral malaria." (PMID 27273825, 2016). "Histopathology and immunohistologic studies detected IL-1β in the brain and liver from a case of fatal cerebral malaria." (PMID 16098232, 2005). "In experimental cerebral malaria, it was found to suppress the production of IL-1β and in Mycobacterium infection; it exerts its anti-inflammatory activity by reducing the expression of both the IL-1β and inducible nitric oxide synthase." (PMID 38750790, 2024). "In cerebral malaria cases, monocytes accumulate at IE sequestration sites in the brain microvascular and the locally produced IL-1β, or other secreted molecules, could contribute to leakage of the blood-brain barrier." (PMID 37141324, 2023). "Postmortem analysis detected increased IL-1β in human brains with cerebral malaria." (PMID 36362246, 2022). "IL-33 produced by oligodendrocytes could further induce IL-1β and inflammatory activity in glial cells, creating a pathological feedback contributing to cerebral malaria." (PMID 32363166, 2020). "In a murine model of experimental cerebral malaria induced by Plasmodium berghei ANKA, ST2 deficiency had a protective effect on the cognitive defects induced by excessive inflammation in the brain in relation with high levels of IL-1β induced by IL-33." (PMID 32571430, 2020). "Drugs targeting caspase-1 and IL-1β are already in clinical use and could be considered for the treatment of cerebral malaria." (PMID 27273825, 2016). "Studies in mice indicate that the inflammatory response to Plasmodium infection and the host susceptibility to experimental cerebral malaria are independent of Nlrp3 inflammasome-dependent caspase-1 activation of IL-1β and IL-18." (PMID 23405174, 2013).
cerebral malaria (continued). "Notably, myeloid-specific JUNB deletion in cerebral malaria models reduces IL-1β/TNF production and shifts macrophages toward a regulated phenotype, improving survival, a finding that dovetails with our observation that JUNB silencing suppresses M1 polarization and NF-κB activation." (PMID 40917776, 2025). "However, the allele frequency of IL1B -31T was not significantly higher in the cerebral malaria patients." (PMID 16098232, 2005). "Cerebral malaria is the most severe form of infection with Plasmodium falciparum characterized by a highly inflammatory response (IFN-γ, IL-1β, TNF-α, iNOS, and IL-6), which contributes to severity of the disease." (PMID 34975479, 2021). "However, neither IL1B -31C>T nor IL1RA VNTR showed any association with cerebral malaria." (PMID 16098232, 2005). "The degree of brain swelling was independent of plasma levels of IL-1β, IL-6, IL-8, and IL-10 in children with cerebral malaria, while IL-12 and TNF were elevated in patients with more severe edema." (PMID 33391257, 2020). "Furthermore, ICAM-1 expression by endothelial cells is enhanced by TNF-α and IL-1β, and ICAM-1 is important in cell adhesion, including adhesion of PRBC, in models of cerebral malaria." (PMID 23300448, 2012). "Taken together, we conclude that the IL1B -31C>T and IL1RA VNTR polymorphisms do not play a crucial role in susceptibility or resistance to cerebral malaria." (PMID 16098232, 2005). "The present results suggest that IL1B -31C>T and IL1RA VNTR polymorphisms do not play a crucial role in susceptibility or resistance to cerebral malaria." (PMID 16098232, 2005). "Drugs targeting IL-1β are already in clinical use, and these or other inhibitors that work elsewhere in the HRPII pro-inflammatory pathway could be considered for the treatment of cerebral malaria." (PMID 28475625, 2017). "While Dostert and colleagues demonstrated a partial protection to experimental cerebral malaria in NLRP3−/− mice, other studies reported that this pathological process occurs independent of NLRP3, ASC, Caspase-1, IL-1R, IL-1β, and IL-18." (PMID 24453977, 2014). "Serum TNF, IFN-γ, IL-1β, IL-6, and IL-10 did not vary based on either TLR2 Δ22 or GTn genotype in children with cerebral malaria." (PMID 22336003, 2012).
chronic heart failure (27 papers, 2008 to 2025). "DOX can cause cardiotoxicity, cardiomyopathy, and congestive heart failure through inflammatory mechanisms, eg by increased prostaglandin E2 and IL-1β." (PMID 35340325, 2022). "In the previous study, TNF-α and IL-1β have been implicated in the pathogenesis of myocardial dysfunction in chronic heart failure, and are suspected to mediate LV remodeling." (PMID 25250773, 2014). "Increased expression of IL‐1β in cardiomyocytes of rats with chronic heart failure leads to substantial interstitial fibrosis and impaired cardiac function." (PMID 39294861, 2024). "In fact, circulating inflammatory cytokines, such as interleukin-1 beta (IL-1β), IL-6, and tumor necrosis factor alpha (TNFα), correlate with clinical events in patients with chronic heart failure." (PMID 34360595, 2021). "TNF-α, IL-1β and IL-6 were the main pro-inflammatory cytokines identified as contributors to the syndrome of chronic heart failure." (PMID 29881417, 2018). "Similar results were observed in a meta-analysis that evaluated of the effects of fish oil supplementation in patients with chronic heart failure, showing that circulating TNFα, IL-1β, and IL-6 decreased after 3 to 12 months of follow-up." (PMID 28599665, 2017). "Monocytes derived from chronic heart failure patients carrying DNMT3A mutations revealed a significantly increased expression of inflammasome genes, such as NLRP3 and IL-1β, compared with the monocytes isolated from chronic heart failure patients with no DNMT3A mutations." (PMID 34299198, 2021). "Both HIV-associated cardiomyopathy and chronic heart failure have been associated with activation of the immune system leading to the pathogenic overproduction of several proinflammatory cytokines, including TNF-α, IL-1β, IL-6 and IL-18." (PMID 21203448, 2010). "Proinflammatory cytokines such as IL-1α, IL-1β, TNF-α, and TNFR2 are elevated in animal models and patients with chronic heart failure." (PMID 40072051, 2025). "In rats with chronic heart failure (CHF), nine inflammatory factors were detected in the SG, and TNF-α and IL-1β levels were increased." (PMID 39328238, 2024). "A study comparing the serum levels of IL-1β in normal patients and those with chronic heart failure classified into functional classes II, III, and IV found that both IL-1β and NLRC4 expression levels increased in the chronic heart failure group." (PMID 39687084, 2024). "Patients in chronic heart failure also exhibit higher levels of pro-inflammatory cytokines including TNF-α, IL-6, IL-1β, and C-reactive protein." (PMID 32125488, 2020). "Additionally, multiple studies have shown that as a result of chronic heart failure, the peripheral circulation and the heart are characterized by intense inflammatory responses, with significant elevations of pro-inflammatory cytokines, including TNF-α, IL-1β, and IL-6." (PMID 36361807, 2022).
cystitis (27 papers, 2011 to 2025). Inflammation of the urinary bladder. "IL-1b is associated with severe acute cystitis in the presence of high bacterial burdens, hence treatment induced inflammation should be limited." (PMID 37965267, 2023). "Taken together, upregulation of TNF-α/NF-κB signaling and the associated increase in IL-1β are underlying downstream mechanisms of magnesium deficiency in the CYP-induced cystitis model." (PMID 32241292, 2020). "In the CYP-induced rat cystitis model, multiplex analysis of cytokine levels also revealed increased inflammation-associated cytokines in the urine and bladder tissue, including IL-6, IL-1β, monocyte chemotactic protein-1, and IL-10." (PMID 24146927, 2013). "For example, in a 2016 study of patients with acute cystitis, the mean IL-1β level was 500 pg/mL, whereas control groups exhibited undetectable levels of IL-1β." (PMID 40986630, 2025). "In the context of UTI, precise IL-1β regulation is essential as IL-1β overactivation promotes cystitis." (PMID 40701780, 2025). "IL-1β is a clinically-relevant urinary marker for interstitial cystitis and has been identified as an immunotherapeutic target for cystitis." (PMID 35720309, 2022). "E. coli-induced up-regulation of TNF-α, IL-6, and IL-1β in cystitis rats were reversed by AAV-shTPRG1 injection, demonstrating that TPRG1 contributed to inflammation in E. coli-induced cystitis rat." (PMID 34998360, 2022). "The importance of NLRP3 in mechanisms of CYP-induced cystitis was demonstrated in previous studies showing that inhibition of NLRP3 prevented increase in urinary IL-1β levels and reduced inflammation and bladder dysfunction in CYP-treated rats." (PMID 35563427, 2022). "In our current koala Chlamydia study, significant down-regulation of IL1β was observed during antibiotic treatment and coincided with the clearance of chlamydial shedding and regression in the signs of chlamydial-induced cystitis." (PMID 31415633, 2019). "This koala chlamydial study provides evidence for the down-regulation of IL1β activation through the regulation of specific genes in reactive oxygen pathways during antibiotic treatment for chlamydial-induced cystitis." (PMID 31415633, 2019). "Recent immuno-genetic studies have identified a molecular basis for acute cystitis, involving Interleukin-1β (IL-1β) as a key regulator of the innate immune response to bladder infection." (PMID 30030504, 2018). "The acute cystitis strain CY-17 was selected for these studies, based on its ability to stimulate IL-1β production and to induce bladder pathology in vivo, in the murine acute cystitis model." (PMID 30030504, 2018). "We have previously shown that inhibition of IL-1β by Anakinra treatment is efficient in the murine acute cystitis model." (PMID 30030504, 2018). "The results show that patients with acute cystitis have more elevated concentrations of IL-1β and MMP-7 in urine, than patients with ABU, identifying IL-1β and MMP-7 as potential biomarkers of acute cystitis." (PMID 27732661, 2016). "We found elevated concentrations of IL-1β in patients with acute cystitis compared to the asymptomatic patient group resulting in a means of 264.5 pg/ml and 1.5 pg/ml, respectively (P < 0.001)." (PMID 27732661, 2016). "Here, we identify acute cystitis as an Interleukin-1 beta (IL-1β)-driven, hyper-inflammatory condition of the infected urinary bladder and IL-1 receptor blockade as a novel therapeutic strategy." (PMID 27732661, 2016). "Asc and Nlrp3 were defined as key resistance determinants and IL-1β activation as a crucial step in the pathogenesis of acute cystitis." (PMID 27732661, 2016). "This hyper-inflammatory phenotype was also observed after infection of Asc-/- mice with the acute cystitis strains CY-92 and CY-17, which triggered high IL-1β responses in vitro." (PMID 27732661, 2016).